GINS4 (GINS complex subunit 4)
Description:
Required for correct functioning of the GINS complex, a complex that plays an essential role in the initiation of DNA replication, and progression of DNA replication forks. GINS complex is a core component of CDC45-MCM-GINS (CMG) helicase, the molecular machine that unwinds template DNA during replication, and around which the replisome is built.
Synonyms: SLD5; MGC14799
Tractability: Small molecule: a structure with a bound ligand is known; it has a binding pocket of medium quality. PROTAC: ubiquitination databases record sites on it.
Gene: Protein-coding gene on chromosome 8 (41,529,218 to 41,545,030, forward strand). Ensembl gene ENSG00000147536.
Subcellular location: Nucleus; Chromosome; Cytoplasm
Subcellular location (Human Protein Atlas): Nucleoplasm; Centrosome
Pathways (Reactome):
DNA Replication: Unwinding of DNA
Gene Ontology:
Molecular function: protein binding
Biological process: DNA replication; double-strand break repair via break-induced replication; DNA-templated DNA replication
Cellular component: CMG complex; GINS complex; nucleus; cytoplasm; nucleoplasm; chromosome
Genetic constraint (gnomAD): Loss-of-function variants: 11 observed, 18.33 expected, observed/expected ratio (o/e) 0.6, 90% interval 0.38 to 0.99. The upper end of that interval is the gene's LOEUF score, 0.99, which puts it in group 4 of 6, group 1 being the genes least tolerant of losing a copy. Missense variants: 153 observed, 177.52 expected, observed/expected ratio (o/e) 0.86, 90% interval 0.75 to 0.99. Synonymous variants: 56 observed, 65.25 expected, observed/expected ratio (o/e) 0.86, 90% interval 0.69 to 1.07.
Homologues: Orthologues: chimpanzee GINS4 (99% identical), macaque GINS4 (99% identical), guinea pig GINS4 (90% identical), dog GINS4 (88% identical), rat Gins4 (88% identical), mouse Gins4 (88% identical), pig GINS4 (78% identical), rabbit GINS4 (75% identical), zebrafish gins4 (70% identical), Drosophila melanogaster Sld5 (38% identical), Caenorhabditis elegans sld-5 (31% identical).
Diseases named in the same sentence as GINS4 in open-access papers:
GINS4 is named in the same sentence as 42 diseases in open-access papers, as found by Europe PMC text mining. Sharing a sentence is not in itself a finding about the gene and the disease. The quoted sentences say what the papers report.
gastric cancer (10 papers, 2013 to 2023). A primary or metastatic malignant neoplasm involving the stomach. "GINS4 has also been associated with the progression and prognosis of lung and stomach cancer." (PMID 35896011, 2022). "The overexpression of GINS4 occurs in breast cancer, colorectal carcinoma, bladder cancer, pancreatic ductal adenocarcinoma, glioma, and gastric cancer." (PMID 37508549, 2023). "Particularly, our previous study indicated that circMLLT10 served as a sponge of miR-509-3-5p, and promoted gastric cancer cell progression through increasing the expression of GINS4 and then activating Rac1 and CDC42." (PMID 34656159, 2021). "Significantly increased GINS4 level has been revealed in a series of human cancers, such as CRC, NSCLC, gastric cancer, bladder cancer, and pancreatic cancer, highlighting the pivotal role of GINS4 in tumorigenesis." (PMID 33842367, 2021). "Collectively, our results demonstrate that GINS4 plays an oncogenic role in gastric cancer, and promotes cancer growth and progression in vivo." (PMID 31754397, 2019). "Taken together, these results demonstrated that GINS4 promotes cell proliferation, cell cycle and metastasis, and suppresses cell apoptosis in gastric cancer." (PMID 31754397, 2019). "Collectively, a novel circMLLT10/miR-509-3-5p/GINS4/Rac1/CDC42 axis was established in gastric cancer growth and progression." (PMID 31754397, 2019). "We also found that GINS4 expression was increased in 61 gastric cancer tissues (Cho gastric statistics, 2011) from the Oncomine database." (PMID 31754397, 2019). "In a previous study, we found ectopic expression of GINS4 in gastric cancer tissues and differential expression in various stages of gastric cancer." (PMID 31754397, 2019). "In summary, our current study provides distinct insights into the roles of the novel GINS4 axis in gastric cancer growth and progression." (PMID 31754397, 2019). "In the present study, we found that the novel gene GINS4 was closely correlated with the clinicopathological features of gastric cancer and promoted gastric cancer growth and progression." (PMID 31754397, 2019). "Differentially expressed genes between above 32 paired samples were screened, and we found that GINS4 expression was significantly higher in gastric cancer tissues than in paired normal gastric tissues (3.74-fold change, P<0.001)." (PMID 31754397, 2019). "IPA revealed that GINS4 plays key roles in cell proliferation, cell cycle, apoptosis, migration and invasion of gastric cancer by Rac1 and CDC42 and their downstream signaling pathways: MAPK/ERK pathway, PI3K/AKT pathway and PTEN pathway." (PMID 31754397, 2019). "GINS4 expression was significantly higher in gastric cancer tissues than in adjacent normal gastric tissues." (PMID 31754397, 2019). "GINS4 is a promising biomarker for early diagnosis and molecular target for therapeutic modalities in gastric cancer." (PMID 31754397, 2019). "First, the level of circMLLT10 expression correlated positively with GINS4 expression and negatively with miR-509-3-5p expression in 61 fresh frozen gastric cancer tissues." (PMID 31754397, 2019). "Second, decrease in circMLLT10 expression increased miR-509-3-5p expression and decreased GINS4 mRNA and protein expression in gastric cancer cells, whereas overexpression of circMLLT10 had the opposite effects." (PMID 31754397, 2019). "Taken together, GINS4 plays key roles in cell proliferation, cell cycle, apoptosis, migration and invasion of gastric cancer through activating Rac1 and CDC42 and their downstream signaling pathways: MAPK/ERK pathway, PI3K/AKT pathway and PTEN pathway." (PMID 31754397, 2019). "Accordingly, the precise biological functions and molecular mechanisms of GINS4 in gastric cancer growth and progression remain unclear, and the mechanisms by which GINS4 expression is modulated remains elusive." (PMID 31754397, 2019).
gastric cancer (continued). "All these results demonstrated that GINS4 acted as a tumor oncogene and played key roles in gastric cancer growth and progression, and may function as a promising target for gastric cancer therapy and diagnosis." (PMID 31754397, 2019). "In addition, the Kaplan-Meier Plotter analysis revealed that overall survival (OS) was substantially lower in gastric cancer patients with high GINS4 expression than in those with low GINS4 expression." (PMID 31754397, 2019). "GINS4 may be a promising biomarker and target for diagnosis and treatment of gastric cancer." (PMID 31754397, 2019). "Additionally, gastric cancer patients with high GINS4 expression exhibited a low OS and DFS." (PMID 31754397, 2019). "There were different pathways, for example, in gastric cancer, via directly combination with Rac1/CDC42, GINS4 activated Rac1/CDC42 and then influence the downstream pathways." (PMID 35896011, 2022). "Data from the Tumor Immune Estimation Resource (TIMER) database demonstrated that GINS4 mRNA expression was significantly elevated in multiple solid tumors, such as HCC, lung squamous cell carcinoma, gastric cancer, cholangiocarcinoma, and esophageal cancer." (PMID 33842367, 2021). "GINS4 was also reported expressed higher in gastric cancer, non-small-cell lung cancer, colorectal cancer and breast cancer than normal tissues." (PMID 35896011, 2022). "Prior studies have demonstrated overexpression of GINS4 in multifarious human cancers tissues and tumor cell lines, including colorectal cancer (CRC), bladder cancer, non-small cell lung cancer (NSCLC), gastric cancer, and pancreatic cancer." (PMID 33842367, 2021). "Specifically, GINS4 could directly activate PI3K/AKT and MAPK/ERK pathways, thus accelerating cell proliferation and apoptosis in gastric cancer and CRC." (PMID 33842367, 2021). "In this study, GINS4 expression was higher in gastric cancer tissues than in normal tissues, and correlated with poor differentiation and advanced T stage, N stage and disease stage." (PMID 31754397, 2019). "Similarly, gastric cancer patients with strongly positive GINS4 staining were characterized with shorter OS and DFS, suggesting that GINS4 may be a promising molecular target in the diagnosis and therapy of gastric cancer." (PMID 33842367, 2021). "Interestingly, high expression of GINS4 is associated with the poor survival of patients with lung ADC and gastric cancer, but not the survival of patients with lung SCC and breast cancer, indicating that GISN4 functions as an oncogene depending on the cancer type." (PMID 31253190, 2019).
lung carcinoma (8 papers, 2019 to 2024). "Further studies have found that LSH can increase the expression of GINS4 by stabilizing its post-transcriptional mRNA level, thus promoting the progression of lung cancer." (PMID 37005430, 2023). "LSH, as an oncogene, has been found to be highly expressed in lung cancer tissues, and is positively correlated with the expression of GINS4." (PMID 37005430, 2023). "This overexpression was equally proof that GINS4 had an important role in lung cancer progression in the xenograft nude mouse model." (PMID 34616505, 2021). "At the same time, GINS4 can promote the progression of lung cancer by promoting the key characteristics of tumor potential and lead to poor prognosis of lung cancer patients." (PMID 34556022, 2021). "The Kaplan-Meier curve also presented that high GINS4 expression predicted undesirable prognosis of all lung cancer patients and lung adenocarcinoma cases." (PMID 33842367, 2021). "Together, these findings indicate the physiological role of GINS4 in the growth, migration, and invasion characteristics of lung cancer cells." (PMID 31253190, 2019). "To further validate the role of GINS4 in lung cancer progression, we generated stable GINS4- knockdown H1299 cells." (PMID 31253190, 2019). "To address the role of GINS4 in lung cancer, we first performed western blotting analysis to determine GINS4 expression in a panel of lung cells and found that GINS4 expression was higher in lung cancer cells than in normal lung cells." (PMID 31253190, 2019). "Results of qRT-PCR confirmed that GINS4 expression was higher in lung cancer cells than in normal lung cells." (PMID 31253190, 2019). "Together, these findings indicate that GINS4 is highly expressed in lung cancer and suggest that it functions as an oncogene in lung cancer progression." (PMID 31253190, 2019). "In the present study, we found that GINS4 facilitates lung cancer progression by promoting cancer cell growth, migration, and invasion, which are the key characteristics of cancer progression." (PMID 31253190, 2019). "In summary, our study highlights the importance of GINS4 in lung cancer migration, invasion, and progression." (PMID 31253190, 2019). "Consistent with our previous findings, we found that LSH was highly expressed in lung cancer tissues and was positively correlated with GINS4 expression." (PMID 31253190, 2019). "Together, these results indicate that GINS4 overexpression promotes the growth, migration, and invasion of lung cancer cells." (PMID 31253190, 2019). "In this study, we examined the physiological role of GINS4 in lung cancer progression and their potential epigenetic mechanisms." (PMID 31253190, 2019). "Together, these results indicate that depletion of GINS4 inhibits the growth, migration, and invasion of lung cancer cells." (PMID 31253190, 2019). "Here we first determined the role of GINS4 in patients with lung cancer, we performed qRT-PCR analysis of an independent panel of 79 primary NSCLC tissues and normal lung tissues." (PMID 31253190, 2019). "Next, we selected HBE, A549, PC9, and H1299 cells to determine the role of GINS4 in lung cancer progression." (PMID 31253190, 2019). "To further determine GINS4 expression level in lung cancer, we performed IHC analysis of tissues obtained from patients with lung cancer." (PMID 31253190, 2019). "Liu Shuang and colleagues investigated lncRNA-microRNA interactions, chromatin modifiers, and ferroptosis in lung cancer, as well as the oncogenic role of GINS4, the tumor-suppressive function of GPR162 in radiotherapy, the impact of AhR on NSCLC, and the targeting of USP8 in HCC treatment." (PMID 39944353, 2024). "The overexpression of GINS4 facilitates lung cancer malignant transformation." (PMID 37508549, 2023). "So far, no study has demonstrated that ferroptosis in lung cancer cell death is caused by the inhibition of GINS4." (PMID 34616505, 2021).
lung carcinoma (continued). "Kaplan–Meier analysis of these patients showed that GINS4 expression was associated with poor overall survival in all lung cancers, and lung ADCs, but not in lung SCCs." (PMID 31253190, 2019). "GINS4 expression was upregulated in the primary lung cancer tissues." (PMID 31253190, 2019). "GINS4 is highly expressed in lung cancer cells and tissues, and GINS4 expression is not association with clinical risk factors, but linked with clinical stage and lymphatic metastasis status." (PMID 31253190, 2019). "To determine whether GINS4 also played a role in lung cancer progression in vivo, we established a xenograft nude mouse model and examined xenograft tumor formation in this model." (PMID 31253190, 2019). "Additionally, multivariate analysis showed that GINS4 expression level in lung cancer was independent of clinical risk factors, such as gender, smoking, tumor differentiation, and tumor size, whereas it was associated with TNM stage and lymph node metastasis." (PMID 33842367, 2021). "To further determine whether GINS4 also played a role in lung cancer progression in vivo, we injected 3 × 106GINS4- knockdown H1299 cells into nude mice and found that GINS4 knockdown significantly decreased the volume, size and weight of tumors derived from these cells." (PMID 31253190, 2019). "Lymphoid-specific helicase (LSH) stabilizes and enhances GINS4 expression via binding to 3’UTR region of GINS4, thus facilitating lung cancer development." (PMID 33842367, 2021). "GINS4 facilitates lung cancer progression by promoting key characteristics of tumor potential, and LSH epigenetically interacts with and stabilizes GINS4 transcripts." (PMID 31253190, 2019). "In the present study, we analyzed the functions of GINS4 besides DNA replication and found that GINS4 promoted EMT, migration, invasion, and metastasis in lung cancer." (PMID 31253190, 2019). "But based on the fact that LSH can inhibit ferroptosis in lung cancer cells and LSH is an upstream signaling molecule of GINS4, it can be speculated that the LSH/GNIS4 axis plays a potentially negative regulatory role in lung cancer cell ferroptosis." (PMID 34616505, 2021). "To further address whether GINS4 promotes tumorigenic potential under the control of LSH, we detected cell growth of lung cancer cells after LSH was transfected into the GINS4-depleted cells." (PMID 31253190, 2019). "However, the relevance of GINS4 in lung cancer has not been determined to date." (PMID 31253190, 2019). "We first stably overexpressed GINS4 in lung cancer cell lines PC9 and H358, and we also found that GINS4 did not affect LSH expression (PC9-GINS4 and H358-GINS4, respectively)." (PMID 31253190, 2019).
bladder cancer (7 papers, 2016 to 2023). "IL-6-induced the upregulation of DNA-methyltransferase (DNMT) inhibits miR-370, leading to high GINS4 expression and tumor growth in bladder cancer." (PMID 33842367, 2021). "Consistent with a recent study indicating that GINS4 expression was high in human bladder cancer tissues and that knockdown of GINS4 expression suppressed cancer cell growth 12, our findings suggested that GINS4 promoted cell growth and metastasis in vitro and in vivo." (PMID 31754397, 2019).
colorectal cancer (7 papers, 2021 to 2023). A primary or metastatic malignant neoplasm that affects the colon or rectum. "GINS4 was found highly expressed in lung, bladder and colorectal cancers, and its downregulation in the bladder and colorectal cancers inhibits growth and cell cycle and accelerate cell apoptosis progression in vitro as well as inhibits tumorigenesis in vivo." (PMID 35167614, 2022). "Downregulation of GINS4 promoted cell cycle arrest, growth inhibition, and apoptosis in colorectal cancer cells." (PMID 33407832, 2021). "Moreover, the relationship between GINS4 and breast cancer, colorectal cancer, hepatocellular carcinoma, and other tumors has also been confirmed." (PMID 34556022, 2021). "KLF4 inhibited colorectal cancer cell proliferation through upregulating p21 and NDRG2 (a molecule downstream of Myc), and downregulating cyclinD1 (the key molecule of cell cycle G1/S extension), GINS complex subunit 4 (GINS4), and IFITM3 (a tumor metastasis-associated molecule)." (PMID 37031197, 2023). "Finally, our results were consistent with a previous report where to confirm the expression of GINS4 was elevated both in colorectal cancer (CRC) cell line and tissue, and upregulated expression of GINS4 can lead to poor prognosis of CRC patients." (PMID 34556022, 2021). "In colorectal cancer, the KLF/GINS4 might be the crucial factor." (PMID 35896011, 2022).